SUZ12P1 (SUZ12 pseudogene 1)
Synonyms: formerly SUZ12P
Gene: Transcribed unprocessed pseudogene on chromosome 17 (30,731,886 to 30,776,402, forward strand). Ensembl gene ENSG00000264538.
Diseases named in the same sentence as SUZ12P1 in open-access papers:
SUZ12P1 is named in the same sentence as 3 diseases in open-access papers, as found by Europe PMC text mining. Sharing a sentence is not in itself a finding about the gene and the disease. The quoted sentences say what the papers report.
prostate carcinoma (2 papers, 2016 to 2023). A carcinoma that arises from epithelial cells of the prostate gland. "We then explored the influence of LINC01138 and SUZ12P1 on apoptosis of prostate cancer cells lines using cell apoptosis assay, and found knockdown of them increased the fraction of apoptotic cells in LNCaP cells lines." (PMID 27556357, 2016). "The results revealed that LINC01138 and SUZ12P1 functioned as oncogenes in prostate cancer." (PMID 27556357, 2016). "SUZ12P1 (SUZ12 [suppressor of zeste 12] pseudogene 1) is a pseudogene, which is a long noncoding RNA promoting the proliferation of and inhibiting apoptosis of prostate cancer." (PMID 36575854, 2023).
tumor (1 paper, 2016). "Our study identified three androgen-responsive lncRNAs, LINC01138, SUZ12P1 and SNHG1 were significantly over-expressed in more metastasis and higher tumor stage patients." (PMID 27556357, 2016).
SUZ12P1 also shares sentences with these, for which no sentence is quoted: colorectal cancer (1 paper).